USP8 (ubiquitin specific peptidase 8)
Diseases named in the same sentence as USP8 in open-access papers (continued):
Sharing a sentence is not in itself a finding about the gene and the disease.
tumor (continued). "USP8 variants were more common in women (94% vs. 76%; p = 0.001), and microadenomas and tumor recurrence were prevalent in the USP8-mutant group (44% vs. 29%; p = 0.04 and 44% vs. 22%; p = 0.0015)." (PMID 39684597, 2024). "Another study explored the potential effect of the USP8 inhibitor RA-9 on USP8-WT human tumor corticotroph cells and murine AtT-20 cells." (PMID 38862897, 2024). "The results showed knockdown USP8 significantly decreased tumor growth and USP8 overexpression enhanced tumor growth." (PMID 38973004, 2024). "Then, we used the DUB-in3, the targeted inhibitor drug of USP8, together with Pemigatinib to feed the nude mouse with xenograft tumor." (PMID 38973004, 2024). "The combined use of a USP8 inhibitor and anti-PD-L1/PD-1 treatment significantly reduced tumor growth and improved survival in mouse colon cancer models." (PMID 38474186, 2024). "Inhibition of USP8 led to diminished tumor invasion, migration, and overall tumor size, enhancing anti-tumor immunity." (PMID 38638430, 2024). "After USP8 depletion, tumor-derived TβRII+ EVs reached nearly undetectable levels; patients with high USP8 expression were resistant to neoadjuvant chemotherapy, suggesting its potential as a biomarker." (PMID 38715050, 2024). "Nevertheless, combining USP8/USP7 inhibitors with PD-1/PD-L1 blockade appears to significantly bolster anti-tumor efficacy." (PMID 38702734, 2024). "Targeting USP8 reduces PD-L1’s level, stimulating cytotoxic T-cells, and bolstering the anti-tumor immune response, which enhances the efficacy of PD-L1-targeted immunotherapy." (PMID 38702734, 2024). "Another USP8 inhibitor, DC-U4106, has also shown anti-tumor activity in xenograft tumor models and is currently in the preclinical stage." (PMID 39223632, 2024). "Combination therapy with a USP8 inhibitor and anti-PD-L1 effectively suppressed pancreatic tumor growth by activation of cytotoxic T-cells and the anti-tumor immunity was mainly dependent on the PD-L1 pathway and CD8 + T cells." (PMID 36539510, 2023). "We observed that the tumor size, tumor volume, and tumor weight in the USP8 inhibitor group decreased significantly compared with those in the control group, and the degree of reduction was similar in the two groups." (PMID 36539510, 2023). "In vivo xenograft and metastasis experiments indicate that inhibition of USP8 suppresses tumor growth and lung metastasis." (PMID 37867237, 2023). "We observed that in the USP8 inhibitor group, the tumor size, tumor volume, and tumor weight decreased significantly compared with those in the control group, and these reductions were more significant in the combination group." (PMID 36539510, 2023). "In several murine tumor models, anti‐PD‐L1/PD‐1 immunotherapy combination with USP8 inhibitor significantly increases the infiltration of CD8+ T cells and suppresses tumor growth." (PMID 37867237, 2023). "Analysis using flow cytometry showed that the amount and function of tumor infiltrated activated T-cells increased in Usp8 KD cell-derived tumors." (PMID 36539510, 2023). "A USP8 inhibitor synergizes with anti-PD-1/PD-L1 treatments, dramatically inhibits tumor growth, and improves survival rates in mouse colon cancer models." (PMID 37415977, 2023). "In several murine tumor models, USP8 inhibitor combination with anti-PD-L1/PD-1 immunotherapy effectively inhibits tumor growth and improves the survival benefit though increasing the infiltration of CD8 + T cells." (PMID 37311739, 2023). "Pharmacological USP8 suppression elicits multiple tumor-inhibitory effects, likely through dysregulating various mRNA expression events, including that of the key cell cycle regulator and oncogenic protein AURKA." (PMID 36816802, 2023). "Another study demonstrated that USP8 deubiquitinates and increases the expression of the type II transforming growth factor-β receptor (TβRII) in tumor-derived extracellular vesicles (TEVs)." (PMID 37415977, 2023).
tumor (continued). "USP8 also promotes tumor metastasis, invasion, and epithelial‐mesenchymal transition in response to TGF‐β/SMAD signaling." (PMID 37867237, 2023). "To explore the anti-tumor role of the USP8 inhibitor via regulation of PD-L1 levels in vivo, we constructed tumor models and administrated the USP8 inhibitor alone or combined with αPD-L1 to mice bearing subcutaneous KPC-derived tumors." (PMID 36539510, 2023). "As a consequence of these findings, it was postulated that piR-1742/USP8/MUC12 played a significant role in the regulation of MUC12-mediated tumor invasiveness via a ‘one-hit/multiple targets’ process." (PMID 37332045, 2023). "In vivo using xenograft and tail vein injection mouse models indicated that inhibition of USP8 significantly reduced tumor growth and inhibited lung metastasis." (PMID 37867237, 2023). "All in all, these researches suggest a potential treatment approach that combines the use of a USP8 inhibitor and PD-1/PD-L1 inhibition to increase anti-tumor activity." (PMID 37658402, 2023). "We observed that the USP8 inhibitor combined with αCTLA-4 group showed reductions compared with the control group in terms of tumor size and tumor weight, but these reductions were more significant in the USP8 inhibitor and αPD-L1 combination group." (PMID 36539510, 2023). "We constructed tumor models and administrated the USP8 inhibitor alone to mice bearing subcutaneous KPC parental cells and KrasG12D KD cells." (PMID 36539510, 2023). "Mutations in genes encoding protein deubiquitinases USP8 and USP48 were determined in tumor tissue in the entire cohort of patients." (PMID 37065760, 2023). "SSTR5 expression was also investigated in murine corticotroph tumor AtT-20 cells, endogenously expressing USP8 wild-type." (PMID 35626057, 2022). "Taken together, these results reveal a molecular mechanism and potential strategy of combination therapy of USP8 inhibitor plus anti-PD-1/PD-L1 antibody to enhance the efficacy of anti-tumor therapy largely through reprograming an inflamed TME." (PMID 35361799, 2022). "Here, we report that inhibiting the deubiquitinase, USP8, significantly enhances the efficacy of anti-PD-1/PD-L1 immunotherapy through reshaping an inflamed tumor microenvironment (TME)." (PMID 35361799, 2022). "Based on these mechanisms, USP8 inhibitor combination with PD-1/PD-L1 blockade significantly activates the infiltrated CD8+ T cells to suppress tumor growth and improves the survival benefit in several murine tumor models." (PMID 35361799, 2022). "Here the authors show that USP8 negatively regulates PD-L1 protein abundance by removing the K63-linked ubiquitination of PD-L1; while USP8 inhibition increases MHC-I expression and triggers anti-tumour immune responses through activating NF-κB signalling." (PMID 35361799, 2022). "We also observed that combining the USP8 inhibitor with anti-PD-1 or anti-PD-L1 therapy significantly retarded the CT26 tumor growth and dramatically improved the overall survival compared with either treatment alone." (PMID 35361799, 2022). "In corticotroph tumor cells, these highly active USP8 mutants rescue epidermal growth factor receptor (EGFR) from ligand-induced ubiquitination and lysosomal degradation and potentiate its signaling resulting in enhanced ACTH synthesis." (PMID 35852754, 2022). "Overall, our findings unveiled a novel mechanism in NSCLC development wherein lncRNA SNHG12 promotes immune escape by binding to HuR to increase mRNA stability and expression of PD-L1 and USP8, thus accelerating tumor growth." (PMID 35658874, 2022). "Conversely, sublines derived from a patient at the first and second recurrence (PEO4 and PEO6) displayed reduced USP8 levels as compared to cells obtained from the platinum-sensitive tumor (PEO1)." (PMID 36578788, 2022).
tumor (continued). "Only three genes were mutated in more than two tumor samples-CDC27 (part of the anaphase-promoting complex, tumor suppressor), USP8 (deubiquitinase gene, cell cycle involvement), and NF2." (PMID 36672540, 2022). "SSTR5 upregulation was observed in USP8 wild-type primary tumor cells transfected with S718del USP8 mutant." (PMID 35626057, 2022). "Expression of PD-L1 and MHC-I on surface of tumor cells, and tumor-infiltrating CD8+ cytotoxic T cells were significantly decreased in Usp8/Traf6 double KO CT26 tumors compared with Usp8-deficient CT26 tumors." (PMID 35361799, 2022). "In vivo, silencing lncRNA SNHG12 mitigated tumor growth and immune escape, decreased PD-L1 and USP8 expression, and increased PD-L1 ubiquitination level in tumor tissues." (PMID 35658874, 2022). "The contradictory observations on the USP8 expression pattern between normal and malignant tissues suggest that USP8 downregulation or upregulation is likely to be tumor type specific." (PMID 34081623, 2021). "The present study provides USP8 G664R variant in vitro functional characterization in AtT-20 cells and demonstrates its possible implication in ACTH-secreting tumor pathogenesis, contributing to enlarge the genetic landscape of CD." (PMID 34439178, 2021). "Compared with normal counterparts, we found that USP8 upregulation was common in tumor tissues of HCC patients (17/20)." (PMID 34081623, 2021). "Inhibition by 17-AAG was stronger in human pituitary ACTH-secreting tumor cells carrying the ubiquitin-specific protease-8 (USP8) mutant in comparison with cells carrying wild-type USP8." (PMID 33537004, 2020). "We believed that overexpressed EGFR provided greater targets for HSP90 inhibitors, therefore 17-AAG manifested a more significant effect on USP8 mutant tumor cells." (PMID 33537004, 2020). "Studies in primary tumor cells with USP8 mutants have shown that gefitinib treatment (EGFR inhibitor) can reduce ACTH secretion." (PMID 33537004, 2020). "At a later time point in the pathogenesis of the tumor, one of these USP8-mutant cells acquires a RASD1 mutation, resulting in a subclone of RASD1-mutant/USP8-mutant cells." (PMID 28487882, 2017). "The different allelic fractions between the USP8 and RASD1 somatic mutations in the studied tumor cells suggest that this ACTH-secreting tumor is genetically heterogeneous." (PMID 28487882, 2017). "A novel mutation, p.K34M, in the GTP-binding region of RASD1 was identified in this tumor, at an allelic fraction (3%) indicative of a subclone with respect to cells containing USP8 p.P720R." (PMID 28487882, 2017). "A somatic mutation in the ubiquitin-specific protease 8 (USP8) gene was reported in about one-thirds to two-thirds of ACTH-secreting adenomas, which is the most prevalent functional tumor found in MPA." (PMID 26869991, 2016). "In xenograft mouse models, the depletion of USP8 inhibited tumor growth, an effect that could be rescued by overexpressing YAP." (PMID 41565619, 2026). "Xenograft models demonstrated that the silence of USP8 significantly inhibited tumor growth." (PMID 41565619, 2026). "To further determine the effects of USP8 variants on the POMC promoter activity, we transfected the POMC luciferase reporter in combination with plasmids expressing USP8-WT and the USP8 variants into murine corticotroph tumor cells." (PMID 40544420, 2025). "Neither the USP8 P681Q mutation identified in our patient nor the hotspot S718P variants affected murine corticotroph tumor cell proliferation (USP8-P681Q vs. USP8-S718P fold change: 1.12 ± 0.03 vs. 1.14 ± 0.07, ns)." (PMID 40544420, 2025). "The tumor was found to have an in-frame PDGFRA::USP8 gene fusion." (PMID 38401149, 2024).
tumor (continued). "In addition, a modulation of the efficacy of immunotherapy can be foreseen because USP8 inhibition has been recently reported to reshape an inflamed tumor microenvironment." (PMID 39430244, 2024). "USP8 was overexpressed in human tumor tissues and correlated with worse survival." (PMID 38973004, 2024). "Not only USP7 inhibitors but also USP8 inhibitors are involved in regulating anti-tumor immunity." (PMID 39223632, 2024). "The results revealed that increased USP8 expression was positively associated with tumor size and TNM stage but did not relate to age, gender, CA19-9, hepatitis infection, tumor differentiation, or lymphatic metastasis." (PMID 38973004, 2024). "Taken together, these results showed that inhibition of USP8 suppressed the tumor malignancies." (PMID 38973004, 2024). "Interestingly, all these genes are related to tumor biology in different ways, and most of them were shown to be involved in USP8-mediated processes." (PMID 39684597, 2024). "Utilizing USP8 inhibitors can enhance anti-tumor efficacy of PD-1/PD-L1 blockade." (PMID 38834869, 2024). "Thus, if the constantly active USP8-mutant enzyme is expressed in the tumor tissue, an increase in activity of Wnt signaling is expected due to the continuous recycling of Fzd receptors on the tumor cell membrane." (PMID 39684405, 2024). "Knockdown of USP8 significantly inhibited tumor proliferation, invasion, and stem-like properties." (PMID 37311739, 2023). "Moreover, a combined strategy comprising a USP8 inhibitor and PD-L1 inhibitor decreases tumor growth and enhances CD8+ T cell mediated killing of cancer cells." (PMID 37415977, 2023). "Similar relationship between USP8 mutations and expression levels were observed in analysis of silent tumors that also revealed a negative correlation between GR and tumor size and higher NR3C1 expression in densely granulated tumors." (PMID 37065760, 2023). "Collectively, targeting USP8 in combination with other anti-tumor drugs might be a potential strategy in cancer immunotherapy to improve patient outcomes." (PMID 36539510, 2023). "Our results indicated that knockdown of USP8 or administration of erastin significantly inhibited tumor growth in vivo, erastin treatment and USP8 depletion in combination significantly inhibited tumor growth in vivo than administration of erastin or USP8 depletion alone." (PMID 37311739, 2023). "Our results suggested that USP8 promotes tumor progression by regulating β-catenin." (PMID 37311739, 2023). "The best tumor suppressor effect was achieved by Usp8 KD combined with αPD-L1." (PMID 36539510, 2023). "USP8 deficiency could exert anti-tumor effects in an immunity-dependent manner and USP8 inhibition could exert a similar tumor suppressive effect in different molecular subtypes of pancreatic cancer." (PMID 36539510, 2023). "The PD-1/PD-L1 inhibitory signal plays an important role in tumor immune escape and is an important target of anti-tumor immunotherapy; therefore, we further assessed whether USP8 interacts with PD-L1." (PMID 36539510, 2023). "Taken together, these results suggested that combining the USP8 inhibitor with PD-L1 blockade could enhance anti-tumor immunity and suppress the growth of pancreatic tumors." (PMID 36539510, 2023). "Furthermore, in vitro, the USP8 inhibitor-αPD-L1 combination therapy promoted activated T cell-mediated tumor cell killing significantly compared with the USP8 inhibitor treatment group or the αPD-L1 therapy group." (PMID 36539510, 2023). "We constructed a stable Usp8 knockdown (KD) KPC cell line using shRNA lentivirus to determine whether and how USP8 deficiency improves anti-tumor immunogenicity." (PMID 36539510, 2023). "The combination of USP8 inhibitor and PD-1/PD-L1 blockade may be potential therapeutic strategy for enhancing anti-tumor efficacy." (PMID 37311739, 2023). "A recent study reported that USP8 could reshape an inflamed tumor microenvironment (TME) to decrease the efficacy of anti-PD-L1/PD-1 immunotherapy." (PMID 37311739, 2023).
tumor (continued). "Accordingly, pasireotide failed to reduce ACTH secretion in the S718P USP8-mutated tumor cells but achieved a strong ACTH reduction in P720R USP8 mutated tumor cells." (PMID 35626057, 2022). "Thus, our study reveals a potential combined therapeutic strategy to utilize a USP8 inhibitor and PD-1/PD-L1 blockade for enhancing anti-tumor efficacy." (PMID 35361799, 2022). "Lastly, our study identified a combined therapeutic strategy that the combination of USP8 inhibitor and PD-1/PD-L1 blockade could significantly reduce tumor growth and increase overall survival rate in different mouse tumor models." (PMID 35361799, 2022). "To test this hypothesis, we utilized the syngeneic mouse MC38 tumor model to examine how the combination of USP8 inhibitor, DUBs-IN-2, with anti-PD-L1 antibody affected tumor growth and mice survival." (PMID 35361799, 2022). "In addition, significant upregulation of PD-L1, p-p65 and MHC-I were also observed in tumor tissues treated with the USP8 inhibitor or combined treatment compared with control treatment." (PMID 35361799, 2022). "Biochemical variables of hypercortisolism and ACTH, as well as tumour size and frequency of invasion of the cavernous sinus, were not different between USP8-mutated and non-mutated subjects." (PMID 33515368, 2021). "Research on primary tumor cells demonstrated that knockdown of USP8 expression or EGFR blockade could inhibit ACTH secretion effectively." (PMID 33537004, 2020). "In view of the nuclear localization of mutant USP8 it remains to be determined whether USP8 also impinges more directly on tumor formation and POMC transcription in the nucleus." (PMID 31845722, 2019). "Fifteen out of 33 tumors (45%) have been found with USP8 gene mutations in the exon 14, indicating that the mutated form of USP8 does not drive the corticotroph tumor progression in NS." (PMID 31487906, 2019). "Moreover, USP8 depletion attenuated tumor growth upon TRAIL injection in a xenograft model using cervical cancer cells." (PMID 31845722, 2019). "Tumor genetic defects in USP8, GNAS, USP48 and BRAF are some of the commonly encountered tissue-specific changes and may explain a larger percentage of the developed tumors." (PMID 31877737, 2019). "However, if the different tumour samples were compared, nuclear USP8 staining was more heterogeneous, and nuclear expression as well as ACTH production within these cells highly correlated." (PMID 28005997, 2016). "In the same time higher nuclear USP8 expression correlated with a smaller tumour size, which may be why it also correlated significantly with a decreased amount of ACTH levels in the blood pre-surgery." (PMID 28005997, 2016). "However, higher nuclear USP8 correlated directly with the intensity of ACTH staining of the tumours (Spearman r = 0.43, p = 0.027*)." (PMID 28005997, 2016). "Importantly, DUB-IN-2 synergized with paclitaxel to enhance anti-tumor efficacy, indicating that targeting USP8 may represent a viable therapeutic tactic to overcome chemotherapy resistance in TNBC patients." (PMID 41565619, 2026). "In addition, the USP8 inhibitor and anti-PDL1 combination therapy could significantly inhibit the tumor growth rate, suggesting the potential application value of USP8 inhibitor in sensitizing immunotherapy of PCa." (PMID 40410130, 2025). "Moreover, it was demonstrated in vivo that MnSx, on the one hand, mediated the activation of tumor autophagy by USP8 via intracellular H2S, while Mn2+ promoted the maturation of dendritic cells, activated cytotoxic T lymphocytes and contributed to tumor eradication." (PMID 39936146, 2025). "Indeed, blockade of USP8 by DUBs-IN-2 synergizes with ICB to retard tumor growth." (PMID 38715050, 2024). "What’s more, we used a xenograft model assay to explore whether USP8 affects tumor growth in vivo." (PMID 38973004, 2024).